CXCL12 (C-X-C motif chemokine ligand 12)
Diseases named in the same sentence as CXCL12 in open-access papers (continued):
Sharing a sentence is not in itself a finding about the gene and the disease.
tumor (continued). "Analysis of bulk tumour mRNA displayed a strong correlation between ACTA2, a marker of MSCs, and matrix remodelling enzymes (MMP2), ECM proteins (VCAN, FN1, COL1A1), immunomodulatory molecules (Serpine1, CXCL12), innate immune cell markers (CD14, ITGAX) and adaptive immune cell markers (CD4)." (PMID 34885111, 2021). "CXCL12 expression was observed mainly in tumor epithelial cells but not in the stromal region." (PMID 33643790, 2021). "We investigated whether TNC influenced expression of the CXCL12 receptors CXCR4 and/or CXCR7 and observed that Cxcr4 levels were higher in TNC‐low (WT/shTNC, KO/shTNC) tumors and in cultured tumor cells upon TNC knockdown, revealing an opposite regulation than Cxcl12 by TNC." (PMID 33988305, 2021). "Thus, strategies to eliminate stoma components, such as CAFs, have been developed, including the use of AMD3100 to deplete the CXCL12+ FAP+ CAF population, which results in a marked infiltration of T cells into the tumor and an increase in the effectiveness of anti-PDL1 therapy." (PMID 33530455, 2021). "A CAF-derived cytokine, CXCL12, interacts with CXCR4 (C-X-C-motif chemokine receptor 4), a protein overexpressed on the surface of cancer cells, whose interplay leads to the induction of the tumor angiogenesis through endothelial cell recruitment into the tumor niche." (PMID 33430277, 2021). "However, CXCL12 and CXCL5 inhibit T cell migration into the tumor, and the array of chemokine receptors present on T cells may not match the tumor chemokine signatures, resulting in poor migration to the tumor site." (PMID 35008832, 2021). "Due to this dramatic down-regulation in chemokine receptors’ expression on TANs, we hypothesized that the chemokines binding CXCR2 and CXCR4 (i.e., CXCL1/CXCL2 and CXCL12, respectively) could be responsible for the differential infiltration of NDN and LDN into the tumor." (PMID 34680231, 2021). "Next, we addressed how TNC induced Cxcl12 by using inhibitors according to established protocols for tyrosine kinase inhibitors (sunitinib), integrin α4β1 and α9β1 (BOP), TGFβ receptor 1 (TGFβRI, GW788388), and Toll‐like receptor 4 (TLR4, Cli95) on tumor cells stimulated with TNC." (PMID 33988305, 2021). "Furthermore, when we treated AMD3100 to the CXCL12 expressing MC38 tumor bearing mouse, CD8+ T cells did not infiltrate to the tumor tissue." (PMID 33643790, 2021). "Combination therapy using anti-PD-1 antibody and an inhibitor of CXCR4, a receptor for CXCL12/SDF-1 that contributes to the maintenance of tumor stem cells, also increases local infiltration of CD4/8 T cells by suppressing Treg and MDSC tumor invasion and prolongs the survival of tumor-bearing mice." (PMID 32707672, 2020). "There appear to be two mechanisms by which CXCL12 affects tumor cell biology: 1) direct stimulation of signaling pathways that promote cancer cell growth, metastasis, and angiogenesis; 2) indirect effects, including the recruitment of CXCR4/CXCR7-positive cancer cells to CXCL12-expressing organs." (PMID 33363463, 2020). "Indeed, BC cells were more clustered and E-cadherin protein levels in tumor cells increased after CXCL12 silencing in CAF-S1 but not in CAF-S4." (PMID 31964880, 2020). "Compared to normal samples, although MAIT cells reduced in HCC, tumor-derived MAIT cells down-regulated genes enriched in the cytokine secretion and cytolytic effect pathways (NFKB1 and STAT5B) and up-regulated genes such as IL8, CXCL12 and HAVCR2 (TIM -3) promote tumor development." (PMID 33574818, 2020). "Mechanistically, the HPC-maintaining capacity of the bone marrow was significantly impaired in tumor-bearing mice, with lower expression of HPC maintaining genes (i.e., CXCL12, SCF, ANGPT1, and VCAM1), and reduced levels of mesenchymal stem cells and CXCL12-producing cells." (PMID 33603745, 2020).
tumor (continued). "Accordingly, administering an inhibitor of CXCR4, the receptor for CXCL12, to the PDA-bearing mice led to the rapid accumulation of effector T cells within the tumor and blockage IL-6 could improve T-cell trafficking, migration and tumor immunosuppression." (PMID 33613544, 2020). "In addition, non-conventional activities of CXCL12 which is a key regulator of tumor progression, and its CXCR4 receptor are described, alongside with the other CXCL12-binding receptor CXCR7 (RDC1)." (PMID 32582148, 2020). "Stromal cells can mediate immune-suppression and protect tumor cells from cytotoxicity via secretion of soluble factors including immune suppressive mediators such as IL-10, TGF-β and PGE2 or growth factors such as stem cell factor (SCF), IL-7, IL-15, CXCL-12 among others." (PMID 32483120, 2020). "CXCL12 and IL7R may be used as a new therapeutic target to study how different immune microenvironments affect cancer pathogenesis and how these genes regulate the interaction between different immune cells and the tumor microenvironment." (PMID 33344233, 2020). "Based on tumor purity, we ascertained that most cytokines are secreted by TAMs and M2 macrophages, and marker sets have significant correlations with CDH11 in STAD, with examples including CCL-2, TGFB1, CXCL12, and MPP2 of TAMs and IL-10, IL1R1, CD163, and MRC1 of M2 phenotype (P < 0.0001)." (PMID 32685527, 2020). "Moreover, during the process of CTCs avoiding anoikis to attach to the endothelium, CTC chemokine receptors CXCR4 and CCR7 bind to CXCL12 and CCL21 on endothelial cells to mediate tumor cell arrest and to resist anoikis by regulating the proapoptotic and antiapoptotic Bmf and Bcl-xL proteins." (PMID 32943996, 2020). "We also found that CXCL12, CCL27, and CCL21 were found in higher quantities in the healthy adjacent tissue (1795.6 ± 700 pg/ml, 242.9 ± 95 pg/ml, and 17285.9 ± 6000 pg/ml, respectively) than in the tumor (325.8 ± 72 pg/ml, 56.7 ± 20 pg/ml, and 2313.6 ± 1,000 pg/ml, respectively)." (PMID 31105699, 2019). "Indeed, elevated levels of SDF-1/CXCL12 in the TME forms a local concentration gradient along which CXCR4-expressing cells, such as bone marrow-derived mesenchymal stem cells (MSCs) can migrate along, homing to the tumour." (PMID 31861782, 2019). "Since RhoA knockdown had no observable effect on tumor angiogenesis, it is possible that the increased CXCL12 expression might drive the paracrine stimulation of the RhoA knockdown cancer cells’ invasiveness." (PMID 31705019, 2019). "Thus, future immune-based strategies may be focused on combinations of different immune checkpoint inhibitors with substances targeting CXCL12/CXCR4 and reversal of local immunosuppression in the microenvironment, converting a ‘cold’ tumor into a ‘hot’ tumor." (PMID 30813533, 2019). "Thus a HA-based dermal filler loaded with CXCL12 can attract and trap CXCR4+tumor cells." (PMID 31332163, 2019). "Several studies have described the presence of other chemokines within the tumor microenvironment (TME), including CCL3, CCL4, CCL5, CXCL12, and growth factors such as colony stimulating factor-1 (CSF1), which may also contribute to monocyte recruitment to tumors." (PMID 31447834, 2019). "This is relevant, because CXCL12 and its receptor CXC chemokine receptor 4 (CXCR4) are present in complex lesions in PAH and CXCL12 promotes aberrant angiogenesis, endothelial proliferation and PH while others have found Wnt1 to be protective from aberrant tumor angiogenesis." (PMID 30883593, 2019). "Therefore, the anti-tumour activity of anti-CXCR4 ADCs might be enhanced in the bone marrow and in other organs with high CXCL12 expression." (PMID 30792442, 2019). "This drastic change of NK cell number was not attributable to changes of CXCR4 and CXCR3 ligand expression levels since CXCL10 expression in the BM was not modulated by NK cell transfer or IL-15 administration, nor was the expression of CXCL10 and CXCL12 by BM tumor cells." (PMID 31699153, 2019).
tumor (continued). "The finding that treatment with AMD3100 did not impair the growth of established tumors (data not shown) supports our interpretation that CXCL12 acts on tumor cells that possess stemness rather than the whole tumor cell population, and is consistent with previous reports." (PMID 29632733, 2018). "EGF may also be involved in reducing docetaxel efficacy in cancer cells; however, a number of other molecules including IL-6, TGFβ, CXCL12, CCL21, VEGF, among others secreted by activated lymphatics are known contributors to drug resistance and these interactions may be tumor cell specific." (PMID 29976154, 2018). "Moreover, in the context of tumour relapse after chemotherapy, MRC1hi, CXCR4hi, Tie2hi VEGFA+ macrophages have been identified as tumour-supporting M2 macrophages localising in perivascular areas where CXCL12 is expressed." (PMID 29760166, 2018). "Tumor-derived soluble mediators such as chemokines (CCL2, CCL5, CXCL12), colony-stimulating factor-1 (CSF-1), TGF-β, IL-10, prostaglandin E2 (PGE2) and metabolites (lactate) likely contribute to the development of TAMs with M2-like phenotype and tumor-promoting properties." (PMID 30563569, 2018). "Although the receptor for CXCL14 is still unknown, it has been reported that CXCL14 is able to synergize with CXCL12 via allosteric modulation of CXCR4, and recruit myeloid DCs to the tumor sites, where it likely promotes their maturation to sustain antitumor immunity." (PMID 30591657, 2018). "In addition, we found a significant increase in Cxcl12 expression in CHOP-treated group but not in its receptor Cxcr4, being relevant, since the CXCL12–CXCR4 axis has been associated with tumor invasion and metastases." (PMID 29410666, 2018). "Interestingly, ACKR3 (formerly CXCR7) is an atypical receptor of CXCL11 and CXCL12, that is not expressed on peripheral blood leukocytes but upregulated by various tumor types, including breast, esophageal and lung squamous cell cancer." (PMID 30319622, 2018). "Interestingly, we observed that murine peritumoral stroma expressed CXCR4 but not CXCL12 in the two tumour xenografts." (PMID 28386296, 2017). "In this case, the blood is the dominant source of CXCL12, not cells in the tumor tissue." (PMID 29117251, 2017). "Once in close proximity to transformed cells in tumoral ducts, CAF favor tumor growth as a result of overexpression of hepatocyte growth factor (HGF), heparin-binding epidermal growth factor (HB-EGF), TGFβ and stromal cell-derived factor (SDF)-1 (also known as CXCL12)." (PMID 28098760, 2017). "However, the expression of CXCL12 mRNA was obviously increased in tumor tissues than that in non-tumor tissues (p<0.01)." (PMID 29254162, 2017). "Nonetheless, expression of CXCL12 could be readily detected in the ACC metastases on the microarrays (see GEO Series accession number GSE90713 per Materials and Methods), and CXCL12 was identified by IHC in some tumor vessels and adjacent normal tissues." (PMID 29088715, 2017). "Interestingly, CXCL12 expression was not homogeneous across the tumour areas of PTC, but prominently increased in areas of collective invasion in PTC." (PMID 28489070, 2017). "Thus, the secretion of CXCL12 (and cytokine secretion in general) is not obligatory for the PT-evoked tumor cell adhesion." (PMID 29100413, 2017). "However, according to our knowledge, our present study is the first to assess the serum concentrations of chemokine CXCL12 in relation to its specific receptor CXCR4 and classical tumor markers for EC (CEA and SCC-Ag) as well as marker of inflammatory states—C-reactive protein (CRP)." (PMID 27041792, 2016). "Among them, C-X-C chemokine ligand 12 (CXCL12) and its receptor C-X-C chemokine receptor type 4 (CXCR4) seem to be involved in the development of several organs, including kidney, and they are also related to tumor growth and metastatic process in many types of cancer." (PMID 27830498, 2016).
tumor (continued). "Peptide R could enhance the efficacy of standard treatments such as radiation, chemo- and anti-VEGF therapies, known to up-regulate CXCL12 and CXCR4 as part of the escape program that favors tumor recurrence and dissemination at distance, restores the vasculature and promotes GAM recruitment." (PMID 27015814, 2016). "Upon tumour antigen pulsing, high levels of chemokines that sustain the recruitment of circulating DCs to inflamed tissues, such as CCL3, CCL4, were expressed, whereas at late time-points constitutive lymphoid chemokine such as CCL2, CCL8, CXCL10, CXCL12 and RANTES were selectively up-regulated." (PMID 26795765, 2016). "Due to its negative effect on CXCR4 expression, tumor intrinsic CXCL12 may be a valuable biomarker in clinical situations that require decision-making." (PMID 27462860, 2016). "No obvious association was observed between CXCL12 expression and lymph node metastasis, suggesting that CXCL12 chemotaxis may only be related to CXCR4 expression on the tumor cell membrane." (PMID 25866764, 2015). "However, blocking of the CXCL12-induced CXCR4-mediated signaling was not able to completely suppress tumor growth or eliminate all cancer cells." (PMID 26083776, 2015). "Without exogenous CXCL11 stimulation, blocking endogenous CXCL11 or CXCL12 alone did not influence tumor growth and angiogenesis, whereas the combined inhibition almost completely abrogated tumor angiogenesis, providing evidence for the proposed close relationship of these chemokines." (PMID 26347749, 2015). "CXCL12 expression was transiently restored using inhibitors of epigenetic repression.Stable reintroduction of CXCL12 in PDAC cells prevented directed cell migration and hepatic metastasis and slowed tumor growthin vitro andin vivo, resulting in increased survival in preclinical models." (PMID 24594697, 2014). "Furthermore, inhibition of CXCL12 and CXCR4 reduces tumor growth by blocking angiogenesis." (PMID 23555768, 2013). "Because of the dichotomy of clinical outcomes observed for SHH MB, we first investigated whether the expression profiles of CXCL12 and CXCR4 in SHH and non-SHH MB is associated with tumor histology (desmoplastic vs. non-desmoplastic) and clinical outcome." (PMID 23497290, 2013). "Homing of WM cells to the bone marrow is regulated, in part, by the BMSC-secreted chemokine SDF-1 (stromal cell-derived factor 1 that is officially designated chemokine [C-X-C motif] ligand 12 or CXCL12), which binds to the CXCR4 receptor (CD184, fusin) on the tumor cells." (PMID 24106612, 2013). "Because both the 2F7 cell line and Namalwa cell lines are similar in that they are EBV(+) BL cell lines, we initially studied CXCR4/CXCL12 in our model, but found no indications that these molecules were important in promoting tumor growth in this model (unpublished results)." (PMID 23936541, 2013). "The tumor cells did not respond to CXCL12 in a chemotaxis assay either." (PMID 22314082, 2012). "In addition to its critical role in tumor cell growth, survival and angiogenesis in multiple cancers, the CXCR4/CXCL12 pair has been shown to mediate homing and metastatic secondary growth in CXCL12-producing organs, such as liver and bone marrow." (PMID 22916293, 2012). "Analysis of CXCL12 was possible in 289 of the 360 cores (80%), with the remainder not available on the cut slide, being lost during antigen retrieval or not demonstrating viable tumour cells in the core." (PMID 22415233, 2012). "Given the recognized role that the CXCL12-CXCR4 pathway plays in chemo-attraction of multiple cell types (lymphocytes, neurons, tumor cells), we evaluated the hypothesis that GBM cells are localized to the peri-endothelial cell domain in a CXCL12-dependent fashion." (PMID 22427929, 2012).
tumor (continued). "In addition, secreted CXCL12 signaling to CXCR4 receptors on macrophages can increase EGFR ligand shedding, and this could also contribute to increased tumor cell motility and invasion." (PMID 22314082, 2012). "The results of these studies indicate that the tumor cells are not activated through autocrine stimulation by CXCL12, but rather that a paracrine loop involving CXCR4-CXCL12 signaling in the tumor microenvironment is needed for EGF-induced in vivo invasion in Neu-YB tumors." (PMID 22314082, 2012). "Moreover, CXCL12 is expressed in a large number of tumors and injured tissues, and the corresponding activation of its receptor, CXCR4, promotes angiogenesis and metastasis of tumor cells." (PMID 21949886, 2011). "Thus, CXCL12 expression by tumor epithelial cells is not in itself a valuable prognostic factor in patients with advanced EOC." (PMID 21410972, 2011). "As there is no increase in CXCR4 expression seen in the MTLn3 JP tumor cells, the response seen in MTLn3 JP tumors to high levels of CXCL12 may reflect initiation of the paracrine loop by tumor-associated macrophages, which express CXCR4." (PMID 22152016, 2011). "Our data show that in the setting of hypoxia and CXCR4 up-regulation in Treg, CXCL12 expression may have the negative consequence of enhancing Treg recruitment and suppressing the anti-tumour immune response." (PMID 21521526, 2011). "CXCL12 may therefore retain tumor cells at the site of production, rather than encouraging them to disseminate and to form secondary tumors in organs at some distance from the original tumor." (PMID 21410972, 2011). "Consequently, the absence of CXCL12 signals the cells to form metastasis in tumours with a high tumour grade with negative ERα status, increasing the probability of patient death." (PMID 20109227, 2010). "Overall, 4 lymph node metastases were CXCL12 negative like their corresponding primary tumour." (PMID 20386750, 2010). "Since CXCL12 expression did not affect the growth of tumor cells in vitro, it seemed likely that inhibition of tumor growth could be due to the effects of CXCL12 on the host rather than on the tumor cells directly." (PMID 20849618, 2010). "However, two metastases revealed CXCL12 immunoreactivity although no CXCL12 expression has been detected in the primary tumour." (PMID 20386750, 2010). "Neither CXCL12(P2G) nor CXCL12 expression affected tumor angiogenesis." (PMID 20849618, 2010). "Thus it is not surprising that CXCL12 and CXCL12(P2G) expression does not affect angiogenesis in this model since the tumor cells are capable of producing VEGF independently of CXCL12." (PMID 20849618, 2010). "Thus, we provide mechanistic evidence that CXCL12/CXCR7 interaction may affect HCC progression by multiple mechanisms including adhesion, invasion, angiogenesis, VEGF production and tumor growth." (PMID 20380740, 2010). "The autocrine action of TNFα may have direct effects on tumor cell spread via acting on the chemokine receptor CXCR4 and also stimulation of blood vessel formation in the peritoneal tumor by inducing expression of VEGF and CXCL12." (PMID 21318181, 2010). "Nevertheless, it has to be kept in mind that gene transcription does not always correlate with mRNA translation and that the tumour biological effect of CXCL12 may also depend on the presence and histoanatomical distribution of CXCR4." (PMID 20386750, 2010). "Since CXCL12 is expressed preferentially in lymph nodes, this may support our finding that CXCR4 expression was significantly correlated with lymph node metastasis in human PTC tumor samples." (PMID 18826577, 2008). "Furthermore, CXCL12 can promote cancerdissemination indirectly by enhancing the vascular supply, since theCXCL12/CXCR4 axis may also promote tumor angiogenesis." (PMID 18779872, 2008).